MAPK8IP2 (mitogen-activated protein kinase 8 interacting protein 2)
Description:
The JNK-interacting protein (JIP) group of scaffold proteins selectively mediates JNK signaling by aggregating specific components of the MAPK cascade to form a functional JNK signaling module. JIP2 inhibits IL1 beta-induced apoptosis in insulin-secreting cells. May function as a regulator of vesicle transport, through interactions with the JNK-signaling components and motor proteins (By similarity).
Synonyms: IB-2; IB2; JIP2; PRKM8IPL
Tractability: PROTAC: ubiquitination databases record sites on it.
Gene: Protein-coding gene on chromosome 22 (50,600,677 to 50,613,981, forward strand). Ensembl gene ENSG00000008735.
Subcellular location: Cytoplasm
Gene Ontology:
Molecular function: MAP-kinase scaffold activity; protein binding; protein kinase binding; amyloid-beta binding; JUN kinase binding; kinesin binding; structural molecule activity; protein-containing complex binding
Biological process: negative regulation of apoptotic signaling pathway; regulation of JNK cascade; behavioral fear response; dendrite morphogenesis; JNK cascade; modulation of excitatory postsynaptic potential; nonassociative learning; regulation of synaptic transmission, glutamatergic; signal complex assembly; social behavior; mating behavior; positive regulation of stress-activated MAPK cascade
Cellular component: cytoplasm; postsynaptic density; neuronal cell body; protein-containing complex
Genetic constraint (gnomAD): Loss-of-function variants: 14 observed, 50.38 expected, observed/expected ratio (o/e) 0.28, 90% interval 0.18 to 0.43. The synonymous counts are far from expectation, so gnomAD's model fits this gene poorly and the ratio says little. Missense variants: 1,043 observed, 992.9 expected, observed/expected ratio (o/e) 1.05, 90% interval 1 to 1.11. Synonymous variants: 609 observed, 458.45 expected, observed/expected ratio (o/e) 1.33, 90% interval 1.24 to 1.42.
Homologues: Orthologues: chimpanzee MAPK8IP2 (99% identical), macaque MAPK8IP2 (97% identical), dog MAPK8IP2 (89% identical), mouse Mapk8ip2 (88% identical), rat Mapk8ip2 (88% identical), guinea pig MAPK8IP2 (87% identical), pig MAPK8IP2 (63% identical), zebrafish mapk8ip2 (58% identical), tropical clawed frog mapk8ip2 (58% identical), Caenorhabditis elegans jip-1 (21% identical), Drosophila melanogaster Aplip1 (17% identical), Drosophila melanogaster Dab (12% identical), and 7 more. Paralogues in human: MAPK8IP1 (36% identical), NOS1AP (8% identical), NUMB (7% identical), NUMBL (7% identical), GULP1 (6% identical), DAB2 (5% identical), FAM43A (5% identical), FAM43B (5% identical), DAB1 (4% identical), LDLRAP1 (3% identical), C1orf226 (0% identical).
Diseases named in the same sentence as MAPK8IP2 in open-access papers:
MAPK8IP2 is named in the same sentence as 28 diseases in open-access papers, as found by Europe PMC text mining. Sharing a sentence is not in itself a finding about the gene and the disease. The quoted sentences say what the papers report.
cervical cancer (3 papers, 2019 to 2023). A primary or metastatic malignant neoplasm involving the cervix. "In addition, MAPK8IP2 was identified to be associated with cervical cancer progression." (PMID 38097567, 2023). "Furthermore, MAPK8IP2 was identified to be associated with the progression of cervical cancer." (PMID 36357836, 2022).
prostate carcinoma (3 papers, 2022 to 2025). A carcinoma that arises from epithelial cells of the prostate gland. "MAPK8IP2, a scaffold protein in the JNK signaling cascade, has been linked to stress response and poor prognosis in prostate cancer." (PMID 41395597, 2025). "circMAML3 and MAPK8IP2 are upregulated in prostate cancer expression and play an oncogenic role, whereas miR-665 is downregulated in prostate cancer and plays an oncogenic role." (PMID 38097567, 2023). "Mechanistically, circMAML3 promotes prostate cancer progression by upregulating MAPK8IP2 expression through sponge miR-665." (PMID 38097567, 2023). "Our research indicates that circMAML3 promotes prostate cancer progression through the circMAML3/miR-665/MAPK8IP2 axis." (PMID 38097567, 2023). "In this study, we discovered that MAPK8IP2 methylation levels in prostate cancer tissues were higher than in normal tissues." (PMID 36357836, 2022). "The prognostic role of MAPK8IP2 in prostate cancer was analyzed using the Cox regression method." (PMID 36357836, 2022). "Therefore, we consider that MAPK8IP2 may serve as a downstream target gene regulated by miR-665 to influence prostate cancer biological behavior." (PMID 38097567, 2023). "However, the biological function of MAPK8IP2 in prostate cancer (PCa) remains unclear." (PMID 36357836, 2022).
ameloblastic carcinoma (2 papers, 2012 to 2021). A rare, cytologically malignant ameloblastoma that may metastasize. "According to Dr. Carcinci's article and due to PKM2 and MAPK8IP2 genes mutations report in esophagus, breast and kidney cancers and availability of the genes studying's kit, genetic study for evaluation of PKM2 and MAPK8IP2 polymorphisms in Ameloblastic carcinoma was performed in our study." (PMID 24551779, 2012). "We report a case series study of ameloblastic carcinoma and ameloblastoma to show the role of PKM2 and MAPK8IP2 polymorphisms in these tumors." (PMID 24551779, 2012). "The presence of PKM2 and MAPK8IP2 gene expression were determined by PCR in ameloblastoma and ameloblastic carcinoma com-paring with normal follicle (controls).c.37G>A polymorphism in PKM2 and the c.196C>T polymorphism in MAPK8IP2 were not recognized in all of the sample cases." (PMID 24551779, 2012).
glioma (2 papers, 2021 to 2022). A benign or malignant brain and spinal cord tumor that arises from glial cells (astrocytes, oligodendrocytes, ependymal cells). "However, MAPK8IP2 was significantly downregulated in GBM, lower brain grade glioma, and paraganglioma, as compared to the normal brain tissues." (PMID 35571016, 2022).
pancreatic cancer (2 papers, 2022 to 2023). "Recent studies have found that MAPK8IP2 may be associated with the prognosis of glioblastoma and pancreatic cancer." (PMID 38097567, 2023). "A recent study found that the expression level of MAPK8IP2 was significantly negatively correlated with DNA methylation in pancreatic cancer (R = -0.507)." (PMID 36357836, 2022). "Recently, it was founded that MAPK8IP2 may be related to the prognosis of the glioblastoma and pancreatic cancer." (PMID 36357836, 2022).
Spinocerebellar Ataxia (2 papers, 2021 to 2022). "MAPK8IP2 was responsible for AKT, ERK, and MAP signaling pathways and was responsible for spinocerebellar ataxia." (PMID 35571016, 2022).
adenoma (1 paper, 2024). A neoplasm arising from the epithelium. "For the validation of some key genes identified in adenoma (IL6ST, GLI3) and carcinoma (MAPK8IP2, CPEB4) patients, survival analysis was completed by using the Kaplan–Meier Plotter." (PMID 39408697, 2024).
bladder urothelial carcinoma (1 paper, 2022). "The results showed significantly higher expression of MAPK8IP2 in 15 types of human cancer, including prostate adenocarcinoma (PRAD), breast invasive carcinoma (BRCA), and bladder urothelial carcinoma (BLCA) (cancer tissues vs. normal tissues)." (PMID 36357836, 2022).
colorectal adenoma (1 paper, 2024). An adenoma that arises from the colon or rectum. "Genes related to CARD11 overexpression in colorectal adenoma patients included IL6ST, GLI3, and PIEZO2, as well as the collagen-related gene family, whilst MAPK8IP2 gene expression was dramatically elevated in CARD11+ carcinoma patients." (PMID 39408697, 2024).
colorectal cancer (1 paper, 2025). A primary or metastatic malignant neoplasm that affects the colon or rectum. "The present study has focused exclusively on the effects of four gene knockdown on drug sensitivity in colorectal cancer cells, without delving into the molecular mechanisms through which three of these key genes – BAMBI, MAPK8IP2, and BMP7 – regulate oxaliplatin sensitivity." (PMID 41395597, 2025).
ovarian carcinoma (1 paper, 2020). A malignant neoplasm originating from the surface ovarian epithelium. "Overall, these observations suggest that ILK regulates the JNK/c-JUN pathway in cisplatin-resistant ovarian cancer via modulation of DUSP8, MARVELD3, PDCD4, MAPK8IP1, MAPK8IP2, and HIPK3." (PMID 32260415, 2020).
tumor (8 papers, 2009 to 2024). "We further used the DNMIVD database to investigate the diagnostic value of CpG sites located within MAPK8IP2 to distinguish tumor samples from normal samples and to perform survival analysis of PCa patients in the low and high groups of DNA methylation of MAPK8IP2." (PMID 36357836, 2022). "At the same time, qRT-PCR analysis also revealed that the expression level of MAPK8IP2 is significantly higher in PCa tissues compared to their corresponding non-tumor tissues." (PMID 38097567, 2023). "We used TCGA (tumor and normal data) and GTEx (normal data) cohorts to analyze the expression of MAPK8IP2 in 33 cancer types (tumor vs. normal)." (PMID 36357836, 2022). "Univariate Cox analysis associated with PFI showed that T stage, N stage, Gleason score, PSA, primary therapy outcome, residual tumor, and MAPK8IP2 affected PFI." (PMID 36357836, 2022). "In the analysis of paired and unpaired samples, MAPK8IP2 expression was significantly lower tin normal tissues than in tumor tissues." (PMID 36357836, 2022). "We used the UCSC Xena and UALCAN databases to compar the DNA methylation levels of MAPK8IP2 between normal and tumor tissues in PCa." (PMID 36357836, 2022). "Moreover, MAPK8IP2 protein expression in tumor and normal tissues was analyzed via the HPA database." (PMID 36357836, 2022). "The heat map suggested that the methylation levels of most CpG sites in primary tumors were higher than those in normal tissues, and the box plot analysis also yielded the same result that primary tumor tissues had higher MAPK8IP2 DNA methylation levels than normal tissues." (PMID 36357836, 2022).
cancer (7 papers, 2019 to 2024). A tumor composed of atypical neoplastic, often pleomorphic cells that invade other tissues. "MAPK8IP2 has been reported to be closely associated with several cancers." (PMID 36357836, 2022). "Carcinoma patients showed a dramatic increase in the expression of MAPK8IP2 in CARD11+ carcinoma patients alongside other cancer-related genes, including EMB, EPHB6, and CPEB4." (PMID 39408697, 2024). "MAPK8IP2 is associated with the MAP kinase pathway, a common cancer pathway, and encodes the JNK interacting protein 2 or JIP2." (PMID 39408697, 2024). "Although studies have shown that the JNK and P38 MAPK pathways are associated with tumors, only a few studies have reported on the role of MAPK8IP2 in cancer." (PMID 36357836, 2022). "In this study, we found that MAPK8IP2 was upregulated in most cancer tissues by analyzing the TCGA and GTEx cohorts of the UCSC database." (PMID 36357836, 2022). "MAPK8IP2 also loses its importance as a biomarker for GBM as it is also observed in all other cancer types." (PMID 35571016, 2022). "Only a few studies have reported the role of MAPK8IP2 in cancer." (PMID 38097567, 2023). "We therefore considered that MAPK8IP2 may play an important role in the development of cancer." (PMID 36357836, 2022). "For example, MAPK8IP2, ADAMTS12, and CHAF1B were upregulated in over five cancer types, while HHIP, PROX1, and PLCG2 were downregulated in over five cancer types." (PMID 35654793, 2022).
MAPK8IP2 also shares sentences with these, for which no sentence is quoted: breast carcinoma (2 papers); cardiac ischemia (2); infection (2); ameloblastoma (1); autism spectrum disorder (1); cardiovascular disease (1); cervical (1); cognitive deficits (1); glioblastoma (1); kidney cancer (1); myocardial infarct (1); neurodevelopmental disorder (1); paraganglioma (1); prostate adenocarcinoma (1); prostate tumor (1).